MMP9 (matrix metallopeptidase 9)
Diseases named in the same sentence as MMP9 in open-access papers (continued):
Sharing a sentence is not in itself a finding about the gene and the disease.
laryngeal carcinoma (continued). "Most researchers have consistent results showing the enhanced expression of MMP-9 in laryngeal carcinoma, but they are not consistent about the relationship between MMP-9 expression and clinical and histopathological features or outcomes of the studied cancers." (PMID 31143300, 2019).
non-Hodgkin lymphoma (12 papers, 2005 to 2025). Distinct from Hodgkin lymphoma both morphologically and biologically, non-Hodgkin lymphoma (NHL) is characterized by the absence of Reed-Sternberg cells, can occur at any age, and usually presents as a localized or generalized lymphadenopathy associated with fever and weight loss. "For instance, increased IL-6, IL-8, IL-1β, and TNF-α can induce MMP-9 expression in malignant non-Hodgkin’s lymphoma, human neutrophils, and corneal epithelial cells respectively." (PMID 30423938, 2018). "In human non-Hodgkin lymphoma a trend toward an unfavourable prognosis and MMP-9 expression has been demonstrated." (PMID 23641796, 2013). "High MMP-9 expression has previously been reported in non-Hodgkin's lymphoma, which can influence the biological behavior and clinical progression of tumor." (PMID 21548969, 2011). "Interestingly, MMP-9 was also identified as a key gene in mantle cell lymphoma, a non-Hodgkin’s lymphoma." (PMID 37446087, 2023). "Furthermore, IL-6 can induce MMP-9 expression in human malignant non-Hodgkin’s lymphomas, and IL-8 can induce MMP-9 expression in human neutrophils through activation of the CXCR2 receptor." (PMID 30423938, 2018). "The expression of MMP9 has been associated with increased aggressiveness and poor prognosis in patients with non-Hodgkin lymphoma, but an influence on prognosis has not been reported in the few studies on cHL." (PMID 24086377, 2013). "The expression of MMP9 has been related to a poorer prognosis in non-lymphoid tumors and in non-Hodgkin lymphoma, but lack of association has been reported in cHL, including a recent Brazilian study with 97 patients." (PMID 24086377, 2013). "We also reported the expression of MMP9 in 158 patients with non-Hodgkin's lymphomas." (PMID 18093334, 2007). "Similar to NCF1 and MMP-9, VDR is linked to modulation of immune cell function and considered a specific marker for HL, but not of B-cell derived non-Hodgkin lymphoma." (PMID 41296384, 2025).
ocular hypertension (12 papers, 2013 to 2025). Abnormally high intraocular pressure. "In agreement, MMP-9 knockout mice developed ocular hypertension." (PMID 36701409, 2023). "Recent studies using knockout mouse models lacking expression of MMP-9 have demonstrated spontaneous increased aqueous outflow resistance and ocular hypertension, in association with deposition of aberrant collagen in the TM51,52." (PMID 29085025, 2017). "Ocular hypertension was further elevated in the TG/MMP-9KO mice compared to the TG/MMP-9 WT mice." (PMID 23559862, 2013). "A recent study has documented that MMP9 knockout mice exhibit an aberrant increase in ECM deposition, reduced AH outflow, and early onset ocular hypertension, suggesting that AS.IV mediated increase in MMP9 levels are critical to effectively controlling ECM turnover in the TM." (PMID 34830390, 2021). "Increased MMP-9 expression/activity in the retina was reported upon induction of ischemia-reperfusion injury, N-methyl-D-aspartic acid (NMDA) and kainic acid-mediated excitotoxicity, optic nerve transection, and ocular hypertension in rodents." (PMID 26451076, 2015).
tongue squamous cell carcinoma (12 papers, 2013 to 2023). A squamous cell carcinoma that arises from the tongue. "The MMP-9 capacity to stimulate tumor invasion and metastatic formations of the cervical lymph nodes was demonstrated in tongue SCC." (PMID 37445908, 2023). "An in vitro study showed the inhibitory effects of grape seed PA on the secretion of MMP-2 and MMP-9 in the tongue squamous cell carcinoma cell line Tca8113, indicating the anti-metastatic capability of PA." (PMID 36330492, 2022). "MiR-34a was also found to inhibit invasion and migration by targeting MMP9 in tongue squamous cell carcinoma." (PMID 33673143, 2021). "The dataset (38 patient samples) exhibited IL-1B (p = 2.67 × 10−6), TGF-β2 (p = 2.23 × 10−4), and MMP9 (p = 0.01) genes to be upregulated in tongue squamous cell carcinoma (SCC) compared with normal tongue tissue." (PMID 32961854, 2020). "In tongue squamous cell carcinoma high MMP9 expression is observed in neoplastic cells at the invasion front." (PMID 24466237, 2014). "Moreover, we have demonstrated that endostatin also directly inhibits the invasion and intravasation of a human tongue SCC cell line and blocks the activity of proMMP-9, suggesting a feedback loop for MMP-9 regulation." (PMID 23365550, 2013). "Silencing uPAR can inhibit the expression of the MMP2, MMP9 and P-ERK proteins in oral and tongue squamous cell carcinoma and attenuate cell proliferation." (PMID 34729105, 2021). "In an invasive tongue squamous cell carcinoma cell line (HSC-3), MMP-9 is colocalized with trypsin-2 in intracellular vesicles." (PMID 23365550, 2013). "In the aggressive human tongue squamous cell carcinoma cell line HSC-3, MMP-2 was only found in its latent form, whereas MMP-9 was found in its active form." (PMID 23365550, 2013).
acute lung injury (11 papers, 2014 to 2025). A condition of lung damage that is characterized by bilateral pulmonary infiltrates (pulmonary edema) rich in neutrophils, and in the absence of clinical heart failure. "Kinetics of MMP-9 have been studied with findings of serum peak at 6 or 12 hours, however these studies were in trauma and acute lung injury." (PMID 35157709, 2022). "We also observed the dynamic equilibrium between MMP-9 and TIMP1, which has also been previously indited for acute lung injury." (PMID 36144218, 2022). "Upregulation the ratio of MMP-9 and TIMP-1 damaged the alveolar–capillary membrane and pulmonary edema in lipopolysaccharide-induced acute lung injury." (PMID 34425812, 2021). "Considering that MMP-9 is a widely expressed matrix metalloproteinase, global blockade or knockout of MMP-9 may not well reflect the local effects of MMP-9 in the development of acute lung injuries." (PMID 33628393, 2021). "Acute lung injury (ALI) is one of the fatal outcomes after exposure to high levels of hydrogen sulfide (H2S), and the matrix metalloproteinases (MMPs) especially MMP-2 and MMP-9 are believed to be involved in the development of ALI by degrading the extracellular matrix (ECM) of blood-air barrier." (PMID 24722316, 2014).
allergic asthma (11 papers, 2012 to 2024). A asthma with a basis in a pathological type I hypersensitivity reaction. "In particular, MMP-9 is associated with the occurrence of asthmatic responses by inducing the production of cytokines, chemokines, and growth factors and has been detected in the sputum of patients with allergic asthma." (PMID 34679759, 2021). "Of these, matrix metalloproteinase (MMP)‐9 and mitogen-activated protein kinases (MAPKs) play a pivotal role in allergic asthma development." (PMID 38745671, 2024). "Along with HDAC1, enhanced expressionof MMP-9, NF-kB and suppressed expression of H3acK9 was observed, which suggested probable relationship between these factors in allergic asthma pathogenesis." (PMID 37316684, 2023). "Similar to these results, the extract of Lonicera japonica decreased activities of MMP-2 and MMP-9 against ovalbumin-induced allergic asthma." (PMID 37107342, 2023). "The expression of MMP-9 was attenuated by diallyl-disulfide-mediated Nrf-2/HO-1 pathway activation in allergic asthma." (PMID 31781316, 2019). "MMP-9, the dominant airway MMP, is up-regulated in allergic asthma, which causes airway remodeling." (PMID 31692453, 2019). "Lim and collaborators reported that phosphorylation of MAPKs activated MMP-9 expression in OVA-challenged mice, and that MMP-9 levels were higher in samples from patients with allergic asthma, which were eliminated by MAPKs inhibitors." (PMID 38745671, 2024). "MMP-9 is significantly increased in bronchoalveolar lavage fluid (BALF) and sputum from patients with allergic asthma." (PMID 24782592, 2014). "Levels of MMP-9 (gelatinase B) are significantly increased in the BALF of OVA-sensitized BALB/c mice, blood and sputum of patients with allergic asthma." (PMID 24223654, 2013).
amyotrophic lateral sclerosis (11 papers, 2011 to 2025). Amyotrophic lateral sclerosis (ALS) is a neurodegenerative disease characterized by progressive muscular paralysis reflecting degeneration of motor neurons in the primary motor cortex, corticospinal tracts, brainstem and spinal cord. "Matrix metalloproteinases 2 and 9 (MMP-2, MMP-9) have been implicated in the pathogenesis of amyotrophic lateral sclerosis (ALS)." (PMID 41009467, 2025). "MMP-9 was associated with demyelination in MS, neuronal cell death in AD, neuroinflammation in PD, dolichoectasia, and neuroinflammation and cell death in amyotrophic lateral sclerosis (ALS)." (PMID 35893290, 2022). "In neuronal and glial cells, preclinical studies showed that MMP9 contributes to the motor neuron cell death in amyotrophic lateral sclerosis (ALS) patients by regulating TNF-α and CD95L expression." (PMID 36544756, 2022). "The pathological role of MMP-9 was also reported in relation to amyotrophic lateral sclerosis." (PMID 33986628, 2021). "MMP9 and CD81 gene products are involved in cell motility and extracellular matrix dynamics, MMP9 expression changes in PD, and amyotrophic lateral sclerosis." (PMID 35085348, 2022).
aneurysmal disease (11 papers, 2019 to 2025). "In line with our data, it has been reported that MMP9-deficient mice in an MI model displayed a reduced rupture rate and attenuated ventricular dilatation, which was associated with reduced macrophage infiltration." (PMID 32271823, 2020). "Neutrophil gelatinase-associated lipocalin (NGAL) is involved in the regulation of MMP9 activity in aneurysmal disease patients." (PMID 37175712, 2023). "In this study, we evaluated the effects of statins on MMP-2, MMP-9, and neutrophil gelatinase-associated lipocalin (NGAL) in both plasma and tissue in patients with aneurysmal disease." (PMID 32111073, 2020). "The vital role of MMP-9 in aneurysmal disease has long been recognized, and our previous studies corroborated the increased expression of MMP-9 in aneurysmal tissues." (PMID 31546645, 2019). "The current study aims to identify the role of MMP-1, MMP-2, MMP-9, and the MMP inhibitor, TIMP-1, in identifying aortic dilation in children with BAV." (PMID 39408865, 2024). "Further functional studies are necessary to elucidate the combined role of TLR4 and MMP9 in AAA development and to address its possible interest as a prognostic or therapeutic target in aneurysmal disease." (PMID 34348653, 2021). "In this study, we evaluated the expression of MMP-2, MMP-9, and NGAL in the plasma and tissue of patients with aneurysmal diseases." (PMID 32111073, 2020). "First, we measured the immune reactivity of MMP-2, MMP-9, and NGAL in the plasma of patients suffering from aneurysmal disease." (PMID 32111073, 2020). "In this pilot clinical trial, we evaluated the effects of statins on MMP-2, MMP-9, and NGAL plasma levels in patients with aneurysmal disease." (PMID 32111073, 2020). "In our previous work, we identified the presence of OLCs in aneurysmal disease and demonstrated a concurrent increase in MMP-9 production, which corroborates previous evidence of the importance of MMP-9 in AAA formation." (PMID 31546645, 2019). "Ventricular dilatation after intraventricular haemorrhage (IVH) has been revealed to result from the widespread deposition of ECM proteins in the subarachnoid space, which can be degraded by MMP‐9, implying that MMP‐9 possibly functions in the resolution of progressive ventricular dilation post‐IVH." (PMID 38643470, 2024). "Hence, the current study proposes to identify whether three MMPs, namely MMP-1, MMP-2, and MMP-9, and the MMP inhibitor, TIMP-1, could be used to predict aortic dilatation in children with BAV." (PMID 39408865, 2024). "In addition to its well-proved antimicrobial capabilities, doxycycline inhibits phorbol-12-myristate-13-acetate-mediated matrix metalloproteinase 8 (MMP-8) and MMP-9 in human endothelial cells, reducing elastin degradation and MMP activity in a model of aneurysmal disease." (PMID 35808704, 2022).
cataract (11 papers, 2013 to 2024). Partial or complete opacity of the crystalline lens of one or both eyes that decreases visual acuity and eventually results in blindness. "MMP-9 activity was determined in lens epithelial cells (LECs), obtained during phacoemulsification from patients with cataracts, by succinylated-gelatin assay." (PMID 35457074, 2022). "This study confirms that AGEs and MMP9 levels are significantly upregulated in DM (+) cataract patients." (PMID 34356319, 2021). "Analysis of the DM (+) cataract group showed that MMP9 and AGE expression levels were significantly higher compared to the control group." (PMID 34356319, 2021). "One of these cytokines is matrix metalloproteinase 9 (MMP-9), which participates in the decomposition of lens epithelial cells (LECs) extracellular matrix and has been correlated with cataract development." (PMID 33261005, 2020). "The studies reviewed here have indicated the efficacy of Nrf2 activation and MMP-9 inhibition as critical therapeutic targets in treating cataracts." (PMID 33261005, 2020). "Matrix metalloproteinase-9 (MMP-9), a proteolytic enzyme, has been implicated in the progression of various kinds of cataracts, including anterior subcapsular cataract, posterior capsular opacification and UVB-induced cataract." (PMID 31076560, 2019). "The concentrations of MMP-1 and MMP-9 in the aqueous humors of 15 cataract patients and 25 DME patients were compared." (PMID 27467659, 2016). "Likewise, the cataracts group presented a δ = 0.438, meaning a medium (defined at the interval 0.330–0.474) difference between tear MMP-9 in the cataracts group and healthy controls." (PMID 35628448, 2022). "Studies demonstrated an increase in MMP-9 expression by stimulating the proteolytic cleavage of latent TGF-β and E-cadherin, leading to epithelial-mesenchymal transition (EMT), which is linked to lens opacity." (PMID 33261005, 2020). "Moreover, we describe the protective role of flavonoids in cataract formation, targeting Nrf2 activation and MMP-9 synthesis inhibition as potential molecular targets in preventing cataracts." (PMID 33261005, 2020). "Compared with the cataract group, the concentration of IL-8, MMP-2, MMP-3, MMP-9, TGFβ-1, TGFβ-3, and TNF-α was significantly increased in subjects with JIAUwG or JIAUwoG." (PMID 29675026, 2018). "We have further shown that TGFβ-induced cataracts can be mitigated through inhibition of the matrix metalloproteinases (MMP) MMP-2 and MMP-9." (PMID 23559862, 2013). "In this study, we observed that MMP9 was upregulated in both CELF1-OE SRA01/04 cells and mouse E14.5 samples, suggest it might affect lens development or cataract pathogenesis." (PMID 35287612, 2022). "Interestingly, our results showed increased expression of MMP2 protein and MMP2/MMP9 activity in total proteins extracts and aqueous humour in 2-month-old K14E6 mice cataracts." (PMID 29888254, 2018). "In addition, the mRNA expression of MMP-2 and MMP-9 was in LECs over 121 times higher for MMP-2 and 274 times higher for MMP-9 in patients with glucocorticosteroid-induced cataracts than in those with non-glucocorticosteroid induced cataracts." (PMID 35457074, 2022). "Furthermore, the analysis of TGF-β-responsive genes by RT-qPCR showed increased expression of collagen (COL1A1), fibronectin (FN1), Snail, matrix metalloproteinase 2 (MMP2), and matrix metalloproteinase 9 (MMP9) in the cataracts of transgenic mice as compared to nontransgenic lens samples." (PMID 29888254, 2018).
cerebral aneurysms (11 papers, 2012 to 2025). "We sought to determine the regulatory events associated with the expression of SPARC, MMP-2 and MMP-9 in ruptured and unruptured human cerebral aneurysms." (PMID 23516489, 2013). "We have previously found that TNF-α can activate a number of pro-inflammatory and matrix remodeling genes in cerebral vascular smooth muscle cells directly implicated in cerebral aneurysm formation, including: MMP-3, MMP-9, MCP-1, VCAM-1, and IL-1β; and IL-1β, VCAM-1 and MCP-1." (PMID 24739142, 2014). "Increased expression of MMP-9 has been observed in cerebral aneurysm walls in humans." (PMID 23259581, 2012). "This study shows that KP‐10 binding to Gpr54 inhibits Egr‐1 expression, thereby suppressing MMP‐9 and VEGF‐A, reducing macrophage infiltration and angiogenesis, and preventing cerebral aneurysm development." (PMID 40384564, 2025). "Increased mRNA expression of both MMP-9 and TIMP-1 in cerebral aneurysms was found in animal models." (PMID 25932641, 2015). "Therapies targeting MMP-9 and TIMP2 may be promising candidates in efforts to prevent the growth and rupture of cerebral aneurysms." (PMID 27349749, 2016).
diabetic cardiomyopathy (11 papers, 2010 to 2025). Diabetic cardiomyopathy is a disorder of the heart muscle in people with diabetes. "Considering impaired cardiac contractility as a major cause of diabetic cardiomyopathy, our results provide a novel role of MMP9 in diabetic hearts and a novel therapeutic approach for ameliorating contractile dysfunction of diabetic hearts by suppressing MMP9." (PMID 27014091, 2016). "In addition, CTS administration could effectively attenuate diabetic cardiomyopathy associated cardiac fibrosis by reducing matrix metalloproteinase-9 (MMP-9) and connective tissue growth factor (CTGF) production via inhibiting STAT3 activity." (PMID 36743695, 2023). "Further, cardiac remodeling biomarkers MMP9 expression (zinc-dependent collagenase) was increased and impaired myocardial contraction in diabetic cardiomyopathy." (PMID 34685620, 2021). "In this study, we investigated the regulation of gelatinase-B (MMP-9) by S. cumini methanol seed extract (MSE) in diabetic cardiomyopathy using real-time PCR, RT-PCR, immunocytochemistry, gel diffusion assay, and substrate zymography." (PMID 33747350, 2021). "A study has reported that exercise improves cardiac function by regulating the concentrations of MMP‐9 and TIMP1 in diabetic cardiomyopathy mice." (PMID 39364701, 2024). "It suggests that MMP-9 and TIMP-3, -4 are largely involved in diabetic cardiomyopathy in Akita." (PMID 20828387, 2010). "In confirmation of the mentioned effect, subjecting a STZ-induced diabetic cardiomyopathy mice model to a 10-week swimming program unregulated the miR-133, improved contractile properties and reduced an extracellular matrix (ECM) regulatory protein; metallopeptidase-9 (MMP9)." (PMID 32405351, 2020).